ATF3 (activating transcription factor 3)
Diseases named in the same sentence as ATF3 in open-access papers (continued):
Sharing a sentence is not in itself a finding about the gene and the disease.
ischemic stroke (continued). "Hence, the effect of silencing ATF3 on ischemic stroke should be validated by extensive representative studies." (PMID 40621504, 2025). "Therefore, the role of ATF3 in these pathways can also be further investigated, in order to order to complement the potential mechanisms of action for ATF3 in ischemic stroke." (PMID 40621504, 2025). "This study has discovered for the first time that silencing ATF3 could alleviate ischemic stroke and improve mitochondrial homeostasis via regulating the MAPK pathway." (PMID 40621504, 2025). "Therefore, this study aimed to silence ATF3 to investigate its downstream mechanism on ischemic stroke." (PMID 40621504, 2025). "In the present study, ATF3 is silenced in OGD/R-induced HT22 cells and ischemic stroke rats, and we found silencing ATF3 could alleviate ischemic stroke and improve mitochondrial homeostasis." (PMID 40621504, 2025). "Additionally, studying the effect of silencing ATF3 on mitochondrial morphology would be useful to understand the details of silencing ATF3 on ischemic stroke." (PMID 40621504, 2025). "The results indicated that silencing ATF3 could alleviate ischemic stroke development and improve mitochondrial homeostasis in rats." (PMID 40621504, 2025). "Importantly, we provide evidence that human serum ATF3 is elevated in clinical patients within 24 h after SCI or ischaemic stroke." (PMID 38649772, 2024). "Furthermore, there was a notable increase in the number of FJC+ degenerated neurons in Atf3 KO mice compared to WT mice after ischaemic stroke." (PMID 38649772, 2024). "To investigate whether ATF3 is also induced in other neurological conditions, we expanded our study to include mice with pMCAO, an ischaemic stroke model." (PMID 38649772, 2024). "Therefore, our data demonstrate that serum ATF3 protein levels can be easily measured as a novel neuron‐specific biomarker for clinical patients with moderate to severe SCI or ischaemic stroke." (PMID 38649772, 2024). "Importantly, ATF3 protein levels in human serum were elevated in clinical patients within 24 hours after SCI or ischemic stroke." (PMID 38649772, 2024). "Additionally, ATF3 protein levels in mouse blood significantly increased 1 day after SCI or ischemic stroke." (PMID 38649772, 2024). "Hence, in vivo and in vitro experiments were conducted to investigate whether silencing ATF3 affected mitochondrial homeostasis and ischemic stroke development via the MAPK signaling pathway using the MAPK pathway agonist anisomycin." (PMID 40621504, 2025). "Furthermore, ATF3 expression was silenced by injection with lv-ATF3 in ischemic stroke rats." (PMID 40621504, 2025). "We injected lentiviral particles into rats 3 weeks before ischemic stroke model induction, and the results showed good silencing efficiency of si-ATF3, which indicating that lentiviral particles integrated into the host genome could persistently inhibit the expression of target genes." (PMID 40621504, 2025). "However, inhibition of ATF3 expression attenuates ischemic stroke progression through ferroptosis." (PMID 40621504, 2025). "Furthermore, our previous study has identified that ATF3 is upregulated in ischemic stroke rats through transcriptome sequencing, and knockdown of ATF3 alleviates ischemic stroke by inhibiting ferroptosis after knocking down ATF3 in ischemic stroke rats." (PMID 40621504, 2025). "However, 3 days after left pMCAO, Atf3 KO mice required significantly more time than WT mice to remove stickers from their right paws, indicating that Atf3 KO mice experienced more severe sensorimotor dysfunction after ischaemic stroke than WT mice." (PMID 38649772, 2024). "Furthermore, ATF3 exhibits a neuroprotective function after SCI or ischaemic stroke." (PMID 38649772, 2024). "In addition, bioinformatics analysis suggested that ATF3 may have protective effect on ischemic stroke." (PMID 36768628, 2023).
ischemic stroke (continued). "Ischemic stroke rats exhibited a higher expression level of AQP4 than that of sham rats (p < 0.01), while silencing ATF3 in MCAO rats significantly downregulated the expression of AQP4 compared with MCAO or lv-NC rats (p < 0.01)." (PMID 40621504, 2025). "ATF3 is an easily measurable, neuron‐specific biomarker for clinical SCI and ischemic stroke, with neuroprotective properties." (PMID 38649772, 2024). "Another limitation is that we measured serum ATF3 in a relatively small number of SCI and ischaemic stroke patients." (PMID 38649772, 2024). "In this study, we demonstrate that ATF3, a member of CREB family transcription factor, is specifically induced in spinal cord or cortex neurons shortly after traumatic SCI or ischaemic stroke, respectively." (PMID 38649772, 2024). "• Activating transcription factor 3 (ATF3) is induced in spinal cord and cortex neurons 1 day after spinal cord injury (SCI) and ischaemic stroke, respectively." (PMID 38649772, 2024). "ATF3 is exclusively induced in spinal cord neurons 1 day post‐SCI and in cortex neurons 1 day after ischaemic stroke." (PMID 38649772, 2024). "• Serum ATF3 is elevated in patients 1 day after SCI or ischaemic stroke, and this elevation correlates linearly with the severity of SCI and ischaemic stroke." (PMID 38649772, 2024). "As a result, this study is only powered to demonstrate the elevation of serum ATF3 levels in moderate to severe SCI and ischaemic stroke patients." (PMID 38649772, 2024). "Further large‐scale clinical studies are warranted to validate the utility of serum ATF3 levels as a biomarker for SCI and ischaemic stroke." (PMID 38649772, 2024). "Taken together, our behavioural and histological results suggest that ATF3 has neuroprotective function after SCI and ischaemic stroke." (PMID 38649772, 2024). "In consistent with previous studies, the present study showed that the expression levels of MFN1 and MFN2 were significantly elevated after silencing ATF3 in OGD/R-treated cells and ischemic stroke rats, suggesting the protective effect of silencing ATF3 on mitochondrial homeostasis." (PMID 40621504, 2025). "Silencing ATF3 attenuates ischemic stroke and improves mitochondrial homeostasis via the MAPK signaling pathway, which shares a novel direction for maintaining mitochondrial homeostasis in ischemic stroke." (PMID 40621504, 2025). "Moreover, Atf3 knockout mice, compared to the wildtype mice, exhibited worse neurological outcomes and larger damage regions after SCI or ischemic stroke, indicating that ATF3 has a neuroprotective function." (PMID 38649772, 2024). "ATF3 protein levels are elevated in the blood in animal models of SCI and ischaemic stroke." (PMID 38649772, 2024). "Our preclinical findings, which showed that ATF3 is elevated in mouse blood after SCI and ischaemic stroke, prompted us to investigate if serum ATF3 could serve as a biomarker for clinical patients with SCI or ischaemic stroke." (PMID 38649772, 2024). "Importantly, ATF3 is detectable and elevated in the serum of patients with SCI and ischaemic stroke." (PMID 38649772, 2024). "Thus, ATF3 is likely a clinical neuron‐specific biomarker that can be used to assess the extent of neuronal injury in patients with acute SCI and ischaemic stroke." (PMID 38649772, 2024). "Importantly, we show that ATF3 protein is detectable and elevated in the blood shortly after SCI or ischaemic stroke." (PMID 38649772, 2024). "Furthermore, serum ATF3 levels are elevated in clinical SCI and ischaemic stroke patients compared to control cohorts." (PMID 38649772, 2024). "In SCI and ischaemic stroke models, we found that ATF3 is not expressed in naive spinal cord or cortex." (PMID 38649772, 2024). "One limitation of our study is that we used the Atf3 global KO mice, and thus we cannot rule out the contribution of ATF3 from the non‐neuronal cells such as microglia in SCI and ischaemic stroke." (PMID 38649772, 2024).
multiple myeloma (9 papers, 2010 to 2023). "ATF3, a transcription factor with a pro-death role in several stressful situations, has been reported to positively regulate apoptosis-inducing genes, such as DR5 and NOXA, and ATF3 knockdown increases the viability of multiple myeloma cells treated by bortezomib." (PMID 34066165, 2021). "Some of these TFs were specifically downregulated in MSCs of active myeloma (RUNX2 and TEAD2), others were already downregulated in precursor myeloma stages (HOXC9 and CEBPD), whereas other TFs, including HOXA2 and ATF3, did not change their expression in any myeloma stages." (PMID 33462210, 2021).
osteosarcoma (9 papers, 2012 to 2025). A usually aggressive malignant bone-forming mesenchymal neoplasm, predominantly affecting adolescents and young adults. "While ATF3’s role in ferroptosis in osteosarcoma has been noted, its impact on the stemness and tumorigenicity of OSCs and osteosarcoma pathophysiology remains unexplored." (PMID 40730548, 2025). "ATF3 mRNA level was elevated in OSCs (GSE152048), and TARGET-OS analysis showed a positive correlation between PDK1 and ATF3 expression in patients with osteosarcoma." (PMID 40730548, 2025). "Activating transcription factor 3 (ATF3) was found to be overexpressed in mouse DRG in response to femoral osteosarcoma, suggesting the potential role of ATF3-expressing capsaicin-insensitive A β mechanosensitive neurons." (PMID 38791867, 2024). "This is consistent with reports of increased expression of ATF3 (a marker for neuronal injury) in peripheral sensory neurons of osteosarcoma bearing compared to control animals and reports that osteosarcomas sampled from human bone lack a distinct nerve supply." (PMID 41228327, 2025). "Additionally, butyrate (HDAC inhibitor) inhibits SLC7A11 transcription by upregulating ATF3 expression and promoting ferroptosis in osteosarcoma cells, thus alleviating osteosarcoma." (PMID 40846688, 2025). "Combined with previous researches, biochanin A may play an antitumor role in osteosarcoma by the ATF3 pathway." (PMID 30723510, 2019). "While further investigation is warranted, our findings position ATF3 as a key downstream effector in the PDK1-mediated regulation of OSC characteristics and osteosarcoma pathogenesis." (PMID 40730548, 2025). "In osteosarcoma, SNHG6 exogenous suppression impairs cell autophagy, apoptosis, colony formation, and invasion through miR-26a-5p sponging, which results in ATF3 (activating transcription factor 3) up-regulation." (PMID 32318335, 2020). "Based on the analysis above, we supposed that biochanin A can suppress the proliferation of osteosarcoma and regulate the expression of BGLAP, BAX, and ATF3, which are involved in regulating DSB response, differentiation and cell death of osteosarcoma." (PMID 30723510, 2019). "In this study, we demonstrated that miR-193a-3p and miR-193a-5p suppress the metastasis of human osteosarcoma cells by repressing Rab27B and SRR expression, through suppressing the TGFβ, Myc/Max and ATF2/ATF3/ATF4 signaling pathways." (PMID 26913720, 2016). "Although we identified the PDK1–glycolysis–ATF3 axis as a key regulator of OSC properties and osteosarcoma malignancy, the precise mechanisms by which PDK1-glycolysis regulates ATF3 expression in OSCs remain unclear." (PMID 40730548, 2025). "Biochanin A can effectively suppress the proliferation of osteosarcoma and regulate the expression of BGLAP, BAX, and ATF3, which may act as the potential therapeutic targets of osteosarcoma." (PMID 30723510, 2019).
Stroke (9 papers, 2022 to 2025). Sudden impairment of blood flow to a part of the brain due to occlusion or rupture of an artery to the brain. "Elevated serum ATF3 levels following intracerebral hemorrhage are closely correlated with disease severity and effectively predict early neurological deterioration, stroke‐associated pneumonia and poor prognosis, reinforcing serum ATF3 as a prognostic surrogate of intracerebral hemorrhage." (PMID 41250979, 2025). "Specifically, PPARα KO led to increased expression levels of Gadd45b, Nppa, Hdc, Lcn2, Il6, Sox4, Marcksl1, Saa3, Ucn2, Met, Dusp10, Elovl7, Ngf, C3, Il11, Hmox1, Alox5, Tnfsf9, Angptl4, Plin2, H19, Csf2rb, Atf3, and Col7a1 following stroke." (PMID 40362325, 2025). "Overexpression of several IEGs including the transcription factors neuronal PAS domain protein 4 (Npas4) and activating transcription factor 3 (Atf3) in the mouse hippocampus via AAVs protects against stroke-induced neuronal damage." (PMID 39482558, 2025). "In stroke rats, silencing ATF3 reduced brain water content, decreased neurological injury and alleviated cerebral infarction." (PMID 40621504, 2025). "In vivo experiments confirmed that Atf3 increased after stroke, and in vitro experiments further demonstrated that Atf3 was elevated considerably in M2 microglia." (PMID 38802919, 2024). "The mice with inhibited ATF3 develop larger ischemic lesions accompanied by more severe neurological deficits and prominent post-stroke inflammation." (PMID 37237015, 2023). "Activating transcription factor 3 (ATF3) was upregulated in a rodent stroke model and later identified as a target of miR-221-3p." (PMID 36289747, 2022). "However, 1 day after pMCAO stroke, ATF3 was strongly expressed in NeuN+ neurons in the peri‐infarct ischaemic brain tissue, with all ATF3+ cells co‐expressing NeuN." (PMID 38649772, 2024). "Similarly, in the corner test, both WT and Atf3 KO mice made approximately 50% left turns at baseline before stroke, but after 3 days of left pMCAO, Atf3 KO mice made significantly more left turns than WT mice." (PMID 38649772, 2024). "Therefore, the results suggested that BCL11B and ATF3 might have synergistic effect promoting functional recovery after stroke." (PMID 37237015, 2023). "Together, these studies support a novel finding and suggest therapeutic potential for both ATF3 overexpression and CTMP knockdown in treating stroke disease." (PMID 36768628, 2023). "The effects of silencing ATF3 on neurological injury, infarction, adenosine triphosphate (ATP), nicotinamide adenine dinucleotide (NAD+), mitofusin 1 (MFN1) and MFN2 were evaluated in stroke rats." (PMID 40621504, 2025). "Interestingly, after a stroke, all FJC+ neurons were also ATF3+, but there were many ATF3+ neurons were FJC−." (PMID 38649772, 2024). "Consistent with our findings in the injured spinal cord, we observed that ATF3 protein was barely detectable in the control cortex without stroke." (PMID 38649772, 2024). "Furthermore, these results suggest the therapeutic potential for both ATF3 overexpression and CTMP knockdown for stroke treatment." (PMID 36768628, 2023).
leukemia (8 papers, 2010 to 2024). A malignant (clonal) hematologic disorder, involving hematopoietic stem cells and characterized by the presence of primitive or atypical myeloid or lymphoid cells in the bone marrow and the blood. "Comparing Atf3 mRNA from CrbnWT versus CrbnV380E/I391V leukemias after treatment with DMSO, CC-885, and CC-90009 gave P values of 0.95, 0.03, and 0.006, respectively." (PMID 35763353, 2022). "Furthermore, activating transcription factor 3 (ATF3), a transcription factor expressed in the human endometrium that can contribute to embryo attachment by transcriptionally increasing leukemia inhibitory factors expression, was significantly up-regulated after tDR-14:32-Glu-CTC-1 inhibition." (PMID 38424649, 2024). "Other transcription factors of the ISR, including ATF3 and CHOP, also modulate this metabolic response in models of leukemia and mitochondrial cardiomyopathy." (PMID 38462161, 2024). "Combination treatment of the MEK/ERK inhibitor UO126 and the HDAC inhibitor SAHA lead to increased apoptosis in leukemia cell lines, however, ATF3 levels were not assessed." (PMID 20828393, 2010).
myocardial ischemia (8 papers, 2013 to 2025). A disorder of cardiac function caused by insufficient blood flow to the muscle tissue of the heart. "During myocardial ischemia/reperfusion injury (MI/RI), ATF3 promotes ferroptosis by upregulating the expression of ACSL4, leading to aggravated cardiomyocyte damage." (PMID 41550926, 2025). "Ferroptosis has been proven to contribute to the progression of myocardial ischemia/reperfusion (I/R) injury and can be inhibited or promoted by ATF3." (PMID 39070785, 2024). "ATF3 was also found to be induced in myocardial ischemia and myocardial ischemia coupled with reperfusion and renal I/R." (PMID 37645012, 2023). "In animal models, the ATF3 is induced in the heart by myocardial ischemia and myocardial ischemia coupled with reperfusion (ischemia-reperfusion)." (PMID 29515366, 2018). "Here, we show that ATF3, a transcription factor that is induced by a variety of stress signals including myocardial ischemia, chemical toxicity of the liver and renal ischemia-reperfusion, down-regulates the expression of AChE, another stress-induced protein." (PMID 29681794, 2018). "Third, ATF3 plays different roles in different phases of cardiac ischemia." (PMID 39195894, 2024).
Arthritis (7 papers, 2012 to 2025). Inflammation of a joint. "Transcription factors c-Fos and Atf3 have been shown to have enhanced expression in inflammatory diseases such as arthritis, which may suggest a reason for their enhanced expression in mandibular-derived monocytes." (PMID 40136529, 2025). "When Atf3 expression is eliminated, symptoms of arthritis decrease considerably." (PMID 39430747, 2024). "One day after induction of SCW arthritis, 3 genes of this panel were upregulated: NAV1.7 (1.7-fold), ATF3 (1.8-fold), and GAP43 (1.9-fold)." (PMID 32854769, 2020). "But neither intra-plantar application of Complete Freund's Adjuvant, antigen induced arthritis nor collagen-induced arthritis could induce ATF-3 expression above the level of ∼2% in lumbar DRG." (PMID 22470467, 2012). "However, it should be noted that in collagen-induced arthritis ATF-3 expression was not affected by anti-TNF therapy." (PMID 22769424, 2012).